DRC9 (dynein regulatory complex subunit 9)
Description:
Component of the nexin-dynein regulatory complex (N-DRC), a key regulator of ciliary/flagellar motility which maintains the alignment and integrity of the distal axoneme and regulates microtubule sliding in motile axonemes. Binds calmodulin when cellular Ca(2+) levels are low and thereby contributes to the regulation of calcium and calmodulin-dependent protein kinase IV (CAMK4) activity; contributes to the regulation of CAMK4 signaling cascades. Required for normal axoneme assembly in sperm flagella, normal sperm tail formation and for male fertility.
Synonyms: IQCG; DKFZp434B227; CFAP122
Tractability: Small molecule: a structure with a bound ligand is known. PROTAC: ubiquitination databases record sites on it.
Gene: Protein-coding gene on chromosome 3 (197,888,220 to 197,960,142, reverse strand). Ensembl gene ENSG00000114473.
Subcellular location: Cytoplasm; Cell projection, cilium, flagellum; Cell projection, cilium; Cytoplasm, cytoskeleton; Cytoplasm, cytoskeleton, flagellum axoneme
Subcellular location (Human Protein Atlas): Actin filaments; Cytosol
Gene Ontology:
Molecular function: calmodulin binding; Hsp70 protein binding
Biological process: cilium movement; cilium organization; flagellated sperm motility; sperm axoneme assembly; spermatid development
Cellular component: cytoplasm; cytosol; extracellular exosome; axonemal nexin link; axoneme; manchette; motile cilium; sperm flagellum; cilium; cytoskeleton
Genetic constraint (gnomAD): Loss-of-function variants: 38 observed, 36.37 expected, observed/expected ratio (o/e) 1.04, 90% interval 0.81 to 1.37. The upper end of that interval is the gene's LOEUF score, 1.37, which puts it in group 5 of 6, group 1 being the genes least tolerant of losing a copy. Missense variants: 384 observed, 438.45 expected, observed/expected ratio (o/e) 0.88, 90% interval 0.81 to 0.95. Synonymous variants: 137 observed, 151.68 expected, observed/expected ratio (o/e) 0.9, 90% interval 0.79 to 1.04.
Homologues: Orthologues: macaque IQCG (82% identical), chimpanzee IQCG (75% identical), pig IQCG (73% identical), dog IQCG (72% identical), rabbit IQCG (71% identical), mouse Iqcg (64% identical), guinea pig IQCG (63% identical), rat Iqcg (62% identical), tropical clawed frog iqcg (40% identical), zebrafish iqcg (28% identical), Drosophila melanogaster CG13972 (17% identical).
Diseases named in the same sentence as DRC9 in open-access papers:
DRC9 is named in the same sentence as 8 diseases in open-access papers, as found by Europe PMC text mining. Sharing a sentence is not in itself a finding about the gene and the disease. The quoted sentences say what the papers report.
male infertility (2 papers, 2022 to 2025). The inability of the male to effect fertilization of an ovum after a specified period of unprotected intercourse. "Both Drc7 and Iqcg (Drc9) knockout mice display disrupted ‘9 + 2’ axonemal architecture, complete sperm immotility, and male infertility." (PMID 41460250, 2025).
infertile (1 paper, 2020). "Further, Iqcg (Drc9) KO male mice were infertile due to severe defects in flagellar formation and immotility of spermatozoa." (PMID 31961863, 2020).
DRC9 also shares sentences with these, for which no sentence is quoted: breast tumors (1 paper); cancer (1); endometrial carcinoma (1); endometriosis (1); Obesity (1); tumor (1).